ABCB1 (ATP binding cassette subfamily B member 1)
Diseases named in the same sentence as ABCB1 in open-access papers (continued):
Sharing a sentence is not in itself a finding about the gene and the disease.
gastric cancer (69 papers, 2002 to 2025). A primary or metastatic malignant neoplasm involving the stomach. "For example, proteasome inhibition was found to reverse the resistance of vincristine‐resistant human gastric cancer cell line by the inhibition of multidrug resistance MDR1 encoded by ABCB1." (PMID 40862469, 2025). "In other studies from Japan, the methylation status of the ABCB1 gene was found to be strongly associated with H. pylori infection and gastric cancer." (PMID 31948121, 2020). "High levels of IL-8 were detected in gastric cancer patients who were insensitive to platinum-based therapy, which was associated with NF-κB activation and increased expression of ATP-binding cassette subfamily B member 1 (ABCB1)." (PMID 34095111, 2021). "In addition, ABCB1 polymorphisms were found to be associated with gastric cancer and were identified as one of the determinants for the successful eradication of H. pylori using triple therapy with lansoprazole, amoxicillin, and clarithromycin." (PMID 31948121, 2020). "Thus, ABCB1 genetic variations seem to play a role in the susceptibility to H. pylori infection and the subsequent development of gastric cancer." (PMID 31948121, 2020). "The lncRNA MRUL (multidrug resistance-related and upregulated lncRNA), for example, regulates ABCB1 expression in gastric cancer, thereby promoting multidrug resistance." (PMID 41195272, 2025). "It was previously revealed that CAFs secrete IL‐8 to promote ABCB1 expression, which, in turn, enhances chemoresistance in gastric cancer cells via activation of the NF‐κB axis." (PMID 38396325, 2024). "For instance, MURL has an enhancer-like role by inducing ABCB1 transcription in MDR gastric cancer cells." (PMID 38927012, 2024). "One investigation revealed that CAFs enhance ABCB1 expression in gastric cancer cells via IL‐8 secretion, suppress cisplatin therapeutic effect, and enhance the occurrence and advancement of gastric cancer." (PMID 38396325, 2024). "In accordance with the experiments conducted in our study, the ABCB1 gene expressions of the compounds applied to gastric cancer cells were found to be significantly low." (PMID 37895364, 2023). "To date, upregulation of the TRIP6 gene occurred in daunorubicin- (EPG85-257RDB) and mitoxantrone-resistant (EPG85-257RNOV) human gastric carcinoma cells, the former cells having also upregulated ABCB1." (PMID 36833223, 2023). "Previously, we revealed that elevated untreated sIL-8 mediates chemoresistence via up-regulation of ABCB1 in gastric cancer." (PMID 35633411, 2022). "miR-206-3p was shown to indirectly repress ABCB1, a multidrug resistance gene, and was shown to reduce Cisplatin resistance in gastric cancer." (PMID 35625614, 2022). "The expression of ABCB1 protein has been shown to be elevated in chemotherapy-resistant gastric cancer tissue compared to chemotherapy-sensitive cancer." (PMID 34306145, 2021). "ETS mediated regulation of ABCB1 was verified in a gastric cancer cell line exhibiting enhanced ABCB1 expression and vincristine resistance using ETS2 overexpression combined with ChIP assays." (PMID 35582031, 2021). "For instance, ectopic miR-129-5p expression can weaken the ADR resistance in gastric cancer cells SGC7901/ADR via silencing ABCB1 (ATP-binding cassette, subfamily B, member 1), ABCC5 and ABCG1." (PMID 32192494, 2020). "A previous study in gastric cancer showed long non-coding RNA MRUL promoted ABCB1 expression in multidrug-resistant cell sublines." (PMID 32670359, 2020). "MDR-related and upregulated lncRNA (MRUL), which is significantly up-regulated in MDR SGC7901/ADR and SGC7901/VCR gastric cancer cells, has been found to promote ABCB1 expression and, thus, resistance to ADR and VCR." (PMID 32192494, 2020). "In another study, it was shown that miR-129 also sensitizes cancer cells to cisplatin, namely in gastric cancer, by regulating ABCB1." (PMID 35582590, 2019).
gastric cancer (continued). "The authors also confirmed that miR-129 expression was significantly downregulated and ABCB1 upregulated in gastric cancer tissues of cisplatin-resistant patients." (PMID 35582590, 2019). "Follow‐up investigations further confirmed that excess CAFs‐mediated secretion led to enhanced serum IL‐8 levels, which, in turn, activated the NF‐κB axis, thereby enhancing the tumour cell resistance gene ABCB1 expression, thus ultimately inducing cisplatin resistance against gastric cancer." (PMID 38396325, 2024). "Hence, IL-8 derived from CAFs involved in promoting chemoresistance in gastric cancer through NF-κB activation and upregulation of ABCB1." (PMID 37065872, 2023). "Recently, two preclinical studies demonstrated the mechanisms by which IL8 mediates platinum resistance by transactivating ATP-binding cassette transporters, i.e., ABCB1 in gastric cancer cells and ABCB5 in tumor-initiating cells of malignant pleural mesothelioma." (PMID 35264742, 2022). "Similarly, ectopic expression of tumor suppressor miR-495 has been found to potentiate PTX-ADR sensitivity in MDR SGC7901R gastric cancer cells through modulating expression of ABCB1." (PMID 32192494, 2020). "In a previous study, ABCB1 C1236T has been shown to be correlated with gastric cancer progression." (PMID 31948121, 2020). "A previous study showed that the activation of the p38 MAPK pathway decreased the expression of the ABCB1 gene in human hepatocellular carcinoma cell lines, whereas inhibition of this pathway decreased the ABCB1 gene expression in human gastric cancer cell lines." (PMID 29061940, 2015). "CAFs elevate human gastric cancer chemoresistance by higher expression of IL-8, which further regulates cell survival pathways including PI3K, Akt, IKb, p65, and ABCB1." (PMID 37065872, 2023). "LncRNA MRUL promotes ABCB1 expression in MDR gastric cancer cells and MRUL depletion can reduce ABCB1 mRNA levels and reverse the MDR phenotype of cells." (PMID 34790665, 2021). "Used in combination with the chemotherapeutic agent daunorubicin in gastric cancer cells, quercetin can down-regulate the ABCB1 gene, reduce the overexpression of P-glycoprotein, and inhibit the efflux of drugs." (PMID 33953682, 2021). "Recent studies show that the cancer stem cell (CSC) markers, such as ABCB1 and CD133, were expressed higher in the diffuse type than in the intestinal type of human gastric carcinoma." (PMID 32368309, 2020). "-The expression of the CSC markers ABCB1, ABCG2, and CD133 differ in gastric cancers with various degrees of differentiation. -Poorly differentiated gastric cancers expressing relatively more CSC markers." (PMID 31024835, 2019). "Recently, a study of lncRNAs in doxorubicin- and vincristine-resistant gastric cancer cells also identified an lncRNA, MRUL, which is located 400 kb downstream of ABCB1 and promotes the expression of ABCB110." (PMID 30568280, 2018). "Classical drug-resistant molecules, such as P-glycoprotein (P-gp)/ABCB1 and multi-drug resistance protein (MRP1)/ABCC1, have been found to play important roles in mediating MDR in some gastric cancers." (PMID 25901126, 2015). "In the present study, we found three members of MDR related ABC transporters (ABCB1, ABCC5 and ABCG1)were targeted by miR-129-5p, which was a hyper-methylated miRNA in gastric cancer MDR cell lines." (PMID 25344911, 2014). "Once the miR-129-5p were hyper-methylated and silenced in gastric cancer cells, the expression of MDR related ABC transporters (ABCB1, ABCC5 and ABCG1) would increase and directly lead to a MDR phenotype." (PMID 25344911, 2014). "In conclusion, the present study demonstrated that miR-129-5p plays an important role in antagonizing MDR in gastric cancer cell lines by directly targeting and inhibiting three MDR-related ABC transporters--ABCB1, ABCC5 and ABCG1." (PMID 25344911, 2014). "CDDP-resistant gastric cancer cells exhibit ABCB1 and CDKN2A gene up-regulation, as compared with CDDP-sensitive gastric cancer cells." (PMID 23672493, 2013).
gastric cancer (continued). "Likewise, hsa-miR-34a-5p enhanced the chemotherapy sensitivity of resistant gastric cancer cells by targeting SIRT1, ABCB1, and ABCC1." (PMID 38057687, 2024). "Moreover, knockdown of HOTAIR inhibited expression of the multidrug-resistance genes ABCB1, ABCC1, and ABCG2 in cisplatin-resistant gastric cancer cells and reduced xenograft tumor growth in nude mice." (PMID 36471329, 2022). "MiR-451 was downregulated in gastric cancer, and its proved target were GATA2, ABCB1, MIF." (PMID 30736753, 2019). "The qRT-PCR experiments were designed to detect the expression levels of the top 5 ranking HAX1, RNF2, PIM3, TPP1 and CAV1 genes in addition to the seed proteins ABCB1, AKT1 and BCL2 in both the SGC7901 gastric cancer cell line and the Adriamycin resistant SGC7901/ADR cell line." (PMID 26039373, 2015). "Moreover, a significantly higher methylation ratio for the ABCB1 promoter in gastric cancer samples than for non-neoplastic mucosa has been reported." (PMID 24380367, 2013).
hepatocellular carcinoma (66 papers, 1996 to 2025). A malignant tumor that arises from hepatocytes. "H19 was the first lncRNA found to be implicated in ABCB1 regulation in human hepatocellular carcinoma (HCC)." (PMID 37781691, 2023). "The parental D12 cells also expressed Abcb1a and Abcb1b in substantial amounts, which can be explained by their hepatoma origin and dexamethasone resistance because hepatocarcinogenesis and dexamethasone treatment have been associated with the activation of Abcb1 genes in rodents." (PMID 24409311, 2014). "Therefore, as the differences in mRNA levels were much higher, gene amplification alone was an unlikely cause of Abcb1 overexpression in the studied rat hepatoma cell lines." (PMID 24409311, 2014). "In a separate study, miR-27a was showed to modulate ABCB1 expression in human hepatocellular carcinoma (HCC) cells through interference with upstream regulator, and downregulation of ABCB1 increased cell sensitivity to 5-FU." (PMID 39114355, 2024). "In hepatocellular carcinoma, for example, the inhibition of ABCB1 has been shown to increase doxorubicin accumulation, reduce drug tolerance, and improve treatment outcomes." (PMID 39679367, 2024). "In hepatocellular carcinoma, miR-223 was reported to modulate multidrug resistance via the downregulation of ABCB1." (PMID 32577098, 2020). "Baicalein induces apoptosis and autophagy and decreases ABCB1 and anti-apoptotic Bcl-xl expression levels on 5-fluorouracil (5-FU) and Epirubicin resistant hepatocellular carcinoma cells (Bel7402/5-FU)." (PMID 31245292, 2019). "To illustrate the potential mechanism, we found that lapatinib remarkably increased the accumulation of doxorubicin and rhodamine 123 in ABCB1-overexpressing hepatocellular carcinoma cells and normal liver tissues in concentration-dependent manners." (PMID 26036634, 2015). "MicroRNA 223 is up-regulated in the multistep progression of Barrett’s esophagus and modulates sensitivity to chemotherapy by targeting PARP1, it also modulates multidrug resistance via downregulation of ABCB1 in hepatocellular carcinoma cells." (PMID 26055874, 2015). "In order to verify our conjecture, we first investigated the effect of lapatinib on increasing drug accumulation in a sensitive hepatocellular carcinoma cells HepG2 and its ABCB1-overexpressing resistant HepG2/Adr subline." (PMID 26036634, 2015). "The rat hepatoma cell lines, col500 and col1000, we used in these studies were selected by colchicine, which is a substrate both for ABCB1 and ABCC1." (PMID 24409311, 2014). "P-glycoprotein (P-gp/ABCB1): Overexpressed in multiple cancers such as acute myeloid leukemia, gliomas, hepatocellular carcinoma, and small cell lung cancer, P-gp reduces intracellular concentrations of chemotherapeutic agents, including paclitaxel, doxorubicin, and vincristine." (PMID 41321948, 2025). "Kaplan–Meier statistics of RNA sequencing data of more than 8000 tumor biopsies of TCGA database revealed that out of 23 tumor entities high ABCB1 expression was significantly correlated with worse survival times for acute myeloid leukemia, multiple myeloma, and hepatocellular carcinoma patients." (PMID 40723843, 2025). "Since anthracyclines are clinically used to treat multiple myeloma, acute myeloid leukemia, and hepatocellular carcinoma, ABCB1 may serve as a prognostic factor for the survival probability of patients affected with these tumor types." (PMID 40723843, 2025). "In human hepatoma cells (HepG2), IS increases the expression and activity of the efflux transporter P-glycoprotein (P-gp) encoded by ABCB1 without modifying the expression of the other transporters." (PMID 38787079, 2024). "Thus, we demonstrated that miRNA-138-1-3p sensitizes sorafenib to hepatocellular carcinoma by targeting PAK5 mediated β-catenin/ABCB1 signaling pathway." (PMID 34340705, 2021).
hepatocellular carcinoma (continued). "In order to determine whether upregulated Abcb1 mRNA levels in drug-resistant rat hepatoma cells were caused by the multiplication of the MDR locus, we compared the copy numbers of the Abcb1 genes in drug-sensitive and drug-resistant cell lines." (PMID 24409311, 2014). "Moreover, various tumors such as renal cell, adrenocortical, colon and hepatocellular cancers express ABCB1 and are practically chemoresistant." (PMID 20492723, 2010). "Another study explored the role of miR-27a in the modulation of ABCB1-mediated MDR in hepatocellular carcinoma (HCC) using the sensitive cell line BEL-7402 and its resistant counterpart, BEL-7402/5-fluorouracil." (PMID 31921125, 2019). "Moreover, miR-223 was demonstrated to rescue the cellular response to anticancer drugs by modulating ABCB1 (ATP-Binding Cassette Sub-Family B Member 1) in hepatocellular carcinoma and targeting PARP1 (poly(ADP-ribose) polymerase 1) in esophageal adenocarcinoma." (PMID 27577078, 2016). "Our group has shown that GH elevates the specific ABC transporters, such as ABCC1, ABCC2, ABCB1, and ABCG2 in melanoma, hepatocellular carcinoma, and pancreatic cancer." (PMID 39123364, 2024). "This involves direct interaction with the 3′-UTR of ABCB1 and suppression of the EGFR-related phosphorylation of the ERK1/2 pathway, ultimately giving rise to increased sensitivity of hepatoma cells to doxorubicin." (PMID 39679367, 2024). "For example, the Hippo signaling pathway could influence regorafenib resistance in hepatocellular carcinoma (HCC) by modulating ABCB1." (PMID 38228910, 2024). "In vitro, siRNA reduce ABCB1/ABCG2 mRNA and ABCB1/ABCG2 protein expression in drug-resistant cancer cells such as U87 glioblastoma cells or hepatocellular carcinoma cells." (PMID 36973040, 2023). "For example, over-expression of miR-223 or miR-298 in doxorubicin (DOX)-resistant hepatocellular carcinoma (HCC) cells or in breast cancer cells, respectively, increased their sensitivity to DOX through ABCB1 (ABC Subfamily B Member 1) downregulation." (PMID 34072348, 2021). "In hepatocellular carcinoma cell lines (MHCCLM3, SMMC-7721), MDR was increased by augmented levels of ABCB1, ABCB1 and ABCG2 when SLUG (SNAI2) was downregulated." (PMID 35582031, 2021). "Two ATP-binding cassette transporters, ABCB1/MDR1 and ABCG2/BCRP, are considered the most critical determinants for chemoresistance in hepatocellular carcinoma." (PMID 34031441, 2021). "ABCB1 and ABCG2 were mainly expressed in well-differentiated hepatoma cells, whereas poorly differentiated hepatoma cells expressed ABCC1 and ABCB2 (TAP1), accompanied by aberrant activation of the Hh signaling." (PMID 33440657, 2021). "P-glycoprotein (P-gp; MDR1, ABCB1) is highly expressed in leukaemia, breast, ovarian, colon, kidney, adrenocortical, and hepatocellular cancers, and its overexpression is inversely correlated with poor clinical prognosis." (PMID 30563925, 2019). "Among 12 hepatoma cell lines, the half maximal inhibitory concentration (IC50) values of regorafenib were positively correlated with any of YAP, Bcl-xL and ABCB1 levels." (PMID 31540262, 2019). "In hepatocellular carcinoma, MDR is mediated by ABCB1, ABCB5, ABCC1, ABCC2, and ABCG2." (PMID 36557005, 2022). "Lapatinib was shown to increase the accumulation of doxorubicin in ABCB1-overexpressing hepatocellular cancer cells and normal liver tissues without altering the protein level of ABCB1." (PMID 26036634, 2015).
hepatocellular carcinoma (continued). "In short, although inhibition of histone deacetylation by TSA-treatment resulted in changes in Abcb1 expression, it did not significantly influence the drug efflux activity of rat hepatoma cells." (PMID 24409311, 2014). "The expression of the two rat Abcb1 genes in the studied hepatoma cells does not change similarly with alterations of the histone acetylation levels at their regulatory regions." (PMID 24409311, 2014). "Moreover, the multi-kinase inhibitor sorafenib (BAY 43-9006) was reported to decrease the mRNA levels of ABCB1 and ABCC1-3 in hepatocellular carcinoma (HCC), suggesting the involvement of the RAF/MEK/ERK pathway in the regulation of multidrug resistant cancer cells." (PMID 29401721, 2018). "In addition to directly interacting with the ABCB1 3′-UTR, miR-338-5p could target the EGFR/ERK1/2 pathway to inhibit the expression of ABCB1, resulting in increased sensitivity of hepatoma cells to DOX." (PMID 29527329, 2018).